DNMT1 (DNA methyltransferase 1)
Diseases named in the same sentence as DNMT1 in open-access papers (continued):
Sharing a sentence is not in itself a finding about the gene and the disease.
infection (37 papers, 2012 to 2024). The state of being infected such as from the introduction of a foreign agent such as serum, vaccine, antigenic substance or organism. "Briefly, there was a general upward trend in mortality risk with increasing DNMT1 expression before the infection point at 2.92; thereafter, the potential relationship reversed." (PMID 38755637, 2024). "Therefore, it is likely that the reduction in DNMT1 levels leads to a loss of methylation on the viral genomes destined for packaging and infection of the new tissue." (PMID 35311536, 2022). "Indeed, several days after the initiation of demethylation (by infection with lentivirus encoding sgRNA targeting DNMT1, or following treatment with 5-azadC), there was an apparent cell death in the hpESC culture." (PMID 34795250, 2021). "On the other hand, the DNMT1 gene encodes for a protein that is responsible for maintaining DNA methylation patterns after replication and it has been shown that some viral and bacterial infections can induce the expression of this gene." (PMID 33808774, 2021). "Accordingly, when DNMT1 was degraded by NS1 after 48 h post-infection, the viral genome was hypomethylated and released from methylation silencing for viral RNA expression and processing, especially those viral RNA transcripts producing capsid proteins." (PMID 39541416, 2024). "At MOI = 3, the expression of DNMT1 tended to decrease, and there was a significant difference 24 h post-infection." (PMID 37631988, 2023). "In the current study, the cagY genotype infection was statistically correlated with increased DNMT1 gene֝ expression." (PMID 36147796, 2022). "The DNMT1 gene expression in the groups of patients with H. pylori cagE+, cagY+, and cagA + genotypes infection compared to patients with H. pylori cagE−, cagY−, and cagA− genotypes infection was 4.09-, 3.08-, and 3.04-fold, respectively (P ≤ 0.05)." (PMID 36147796, 2022). "On the other hand, the biopsy samples with infection of H. pylori cagA, cagY, and cagE genotypes revealed a direct correlation along with increased DNMT1 gene expression." (PMID 36147796, 2022). "BAFT and ISG15 are involved in processes related to immune response, while DNMT1 is related to the preservation of methylation patterns, and its expression is modulated by pathogen infections." (PMID 33808774, 2021). "Decreased expression of DNMT1 has been observed in primary GECs after infection with P. gingivalis or F. nucleatum." (PMID 33256844, 2020). "Levels of DNMT1 mRNA fell markedly at 6 h post-infection, while those of DNMT3a and DNMT3b fell only slightly at 12 h post-infection." (PMID 29717211, 2018). "It has been demonstrated that DNMT activity, DNMT1 expression, and DNA methylation level are increased in uroepithelial cells after infection with uropathogenic Escherichia coli." (PMID 27661616, 2016). "Next, different MOIs (1, 2, 3 and 5) have been used to verify whether the inhibition of DNMT1 was related to the initial infection dose of IAV." (PMID 37631988, 2023). "To further verify whether there were other molecular mechanisms for down-regulating DNMT1 in CA07 infections in addition to miRNA-142-5p, we investigated the complex signaling pathways related to IAV infection and epigenetic mechanisms." (PMID 37631988, 2023). "Exterior factors including long-term infections, in this study Helicobacter pylori infection, could change host cells' epigenetics by affecting DNMT1 gene expression." (PMID 36147796, 2022). "This strategy allowed us to detect three genes, namely BAFT, ISG15 and DNMT1, that clearly differentiate groups of infection with high accuracy (training set: area under the curve (AUC) 0.86 (sensitivity: 0.81; specificity: 0.87); testing set: AUC 0.87 (sensitivity: 0.82; specificity: 0.86))." (PMID 33808774, 2021). "Interestingly, shDNMT1 infection alone significantly increased cellular cholesterol efflux, suggesting high endogenous activities of DNMT1." (PMID 27295295, 2016).
infection (continued). "At every 24 hours within 4 days after lentiviruses infection of SiHa and CaSki, we used Q-PCR to analyze the expression of E6, E7, DNA methyltransferase genes (DNMT1, DNMT3A, DNMT3B and DNMT3L), and tumor suppressor genes (MT1G, NMES1, RRAD, SFRP1, SPARC and TFPI2)." (PMID 26329329, 2015). "However, in these studies, GECs were exposed to DNMT1 inhibitors for a short period before infection (4 h), which may be insufficient to induce DNA hypomethylation." (PMID 33256844, 2020). "The Western blot (with HA as an infection marker) and qRT-PCR analyses that followed confirmed that CA07 infection decreased the DNMT1 protein level in A549 cells and that the difference was significant compared with the control group (p < 0.05)." (PMID 37631988, 2023). "This suggests that long-term infection disrupts de novo methylation (via DNMT3A gene deregulation) and maintenance of methylation during cell proliferation (via DNMT1 gene deregulation)." (PMID 35531332, 2022). "In our result, we have shown a significant decrease in levels of DNMT1, DNMT3A, and DNMT3B following SARS-CoV-2 in vitro infection." (PMID 33679887, 2021). "When compared between IAPV and control samples, DNMT1 (GB47348) was significantly down-regulated 1.5-fold (p < 0.001) at 20 h post-infection, and 1.7-fold (p < 0.001) at 48 h post-infection." (PMID 33101388, 2020). "Cultures that showed near-complete infection as measured by GFP expression were cultured for 3–5 days and evaluated for expression of USP7 and DNMT1 by immunoblot." (PMID 29482658, 2018). "Upon infection with recombinant EBV, GC cell lines MKN1 and MKN7 showed DNMT1 upregulation along with hypermethylation of the regulatory region of the PTEN gene." (PMID 29691341, 2018). "We proposed that changes in methylation induced early in infection by HIV potentiate the alterations in the DNA methylation machinery, particularly induction of DNMT1 expression, which is further altered after METH exposure." (PMID 25054922, 2014). "Recently, it was also shown that following infection of germinal centre (GC) B cells, EBV down-regulates DNMT1 and DNMT3B expression, whilst upregulating DNMT3A." (PMID 23189137, 2012). "Similarly, further immunofluorescence experiments confirmed the down-regulation of DNMT1 in A549 cells after CA07 infection, with NP as an infection marker." (PMID 37631988, 2023). "Gastric biopsy specimens of patients with the H. pylori cagY+, cagE+, and cagA + genotypes infection showed a negative correlation with the DNMT1 gene ΔCt." (PMID 36147796, 2022). "Next, expression of these three DNMTs protein was detected by western blotting; the results were consistent with mRNA levels, showing that DNMT1, but not DNMT3a and DNMT3b, protein was down-regulated obviously at 12 h post-infection." (PMID 29717211, 2018). "Moreover, knockdown of DNMT1 promoted the transcription of IRF3 in cells either with or without VSVΔ51 infection." (PMID 37880243, 2023). "The results showed that the expression of DNMT1 was down-regulated 24 h post-infection for all three IAV infections, and the differences were significant during CA07 (1/3 expression level of the mock group) and PR8 (1/2 expression level of the mock group) infection." (PMID 37631988, 2023). "Quantitative measurement of the mRNAs of DNMT1 DNMT3a and DNMT3b by real-time qRT-PCR reveals that the mRNAs of all the three major form of DNMTs are present in PT cells and PPV infection does not change their levels significantly." (PMID 24392033, 2013).
hematological malignancies (33 papers, 2011 to 2026). "DNMT1 has been a focal point for mechanistic studies Involving decitabine and bortezomib in hematological malignancies, nevertheless mechanisms regarding DNMT3a and DNMT3b activity remain largely unclear upon treatment with these drugs." (PMID 34358067, 2021). "Inhibition of DNMT1 had been suggested as one of the targeted therapies for hematologic malignancies." (PMID 19897545, 2011). "Indeed, the reversal of aberrant hypermethylation by inhibiting DNMT1 promoted anticancer activity, especially in hematologic malignancies; this finding partially explains the relevance of DNMT1 as a therapeutic target." (PMID 36980623, 2023). "Although mutations in epigenetic factors like DNMT1/3a and TET2 are common in hematological malignancies, there are mixed findings when it comes to whether such genetic alterations are principal contributors to secondary resistances." (PMID 34358067, 2021). "As DNMT1 functions during DNA replication to copy methylation patterns from parental strands to daughter strands, DNMT1 inhibitors are effective against rapidly cycling cells of hematological malignancy, but have limited effectiveness against solid tumors, which generally replicate more slowly." (PMID 35158795, 2022).
cardiovascular diseases (12 papers, 2016 to 2025). "Polymorphisms in methylenetetrahydrofolate reductase (MTHFR) and deoxyribonucleic acid methyltransferase-1 (DNMT-1) genes are linked to cardiovascular diseases, yet their specific roles in ACS pathogenesis remain unclear." (PMID 40283597, 2025). "Additionally, DNMT1-mediated epigenetic regulation of immune responses may critically impact cardiovascular disease pathogenesis, given its close association with immune signaling pathways, such as T-cell receptor (TCR), and B-cell receptor (BCR)." (PMID 40405297, 2025). "Meantime, the interrelations study of c‐Myc and DNMT1 on the regulatory mechanisms of MFN2 will provide a therapeutic target for Hcy‐induced cardiovascular diseases." (PMID 31104361, 2019). "Procainamide, a specific DNMT1 inhibitor, has been widely studied under this category of drugs, primarily due to its existing approval to treat cardiovascular diseases." (PMID 27589566, 2016). "The bulk of this review discussed the roles of DNMT1, DNMT3A, and DNMT3B in both germline and hematopoietic cells in the development of PAH and cardiovascular diseases." (PMID 37947606, 2023).
adenocarcinoma (10 papers, 2008 to 2025). A common cancer characterized by the presence of malignant glandular cells. "The relative abundances of reelin, DNMT-1 and ApoER2 mRNAs were determined by PCR in the colon samples cited above and in the tissue adjacent to mouse colon polyps and adenocarcinomas." (PMID 36290310, 2022). "Our studies with the second set of clinical samples seem to suggest that there is a significant correlation between DNMT1 and Survivin in adenocarcinoma." (PMID 27177222, 2016). "We considered of interest to find out whether the tissue surrounding (adjacent to) the colon polyp and adenocarcinoma exhibits changes in reelin, DNMT-1 and ApoER2 mRNA expression." (PMID 36290310, 2022). "DNMT-1 and ApoER2 might downregulate reelin expression in both types of adenocarcinomas." (PMID 36290310, 2022). "DNMT1, DNMT3A, and DNMT3B, which are critical for establishing patterns of DNA methylation, are frequently upregulated among adenocarcinomas." (PMID 40191732, 2025). "DNMT-1 expression in the tissue adjacent to any of the three types of lesions did not significantly differ from that in a healthy colon, nor in the polyps, but it was lower than in the adenocarcinomas." (PMID 36290310, 2022).
breast (9 papers, 2012 to 2022).
hematological cancers (9 papers, 2014 to 2025). "Increased expression of DNMT1 is often found in several solid and hematological cancers and has been linked with a poor prognosis, especially in solid cancers." (PMID 36059621, 2022). "The study not only displays the association of AID and DNMT1 and identifies a novel biological function of AID, but also provides a novel role of a DNMT inhibitor for treating AID-positive hematopoietic cancers." (PMID 24457556, 2014). "The study not only displays the association of AID and DNMT1 and identifies a novel biological function of AID, but also provides novel information regarding the use of DNMT inhibitors to treat AID-positive hematopoietic cancers." (PMID 24457556, 2014). "In addition, some proteins such as the fatty acid-binding protein 4 (FABP4) and nucleolin were also found to regulate DNMT1 levels in hematological cancers." (PMID 36059621, 2022). "Overexpression of DNMT1, DNMT3A, and DNMT3B has been observed in many solid and hematological cancers, including MM." (PMID 36059621, 2022). "In AID-overexpressing hematopoietic cancer cells, however, AID interacts with and stabilizes DNMT1, which blocks the anticancer effect of Zeb due to its inability to downregulate AID and hinders DNMT1 degradation." (PMID 24457556, 2014).
neurological disorders (9 papers, 2019 to 2025). "DNMT1 mutation has been identified in neurological diseases, and DNMT3A mutation was observed in Tatton–Brown–Rahman syndrome, which involves overgrowth and intellectual disability." (PMID 34299198, 2021). "Exome sequencing studies revealed several mutations in DNMT1 that result in two adult onset, progressive neurological disorders." (PMID 31091831, 2019). "Mutations and altered expression of Dnmt1 and Tet2 are associated with age-related cognitive decline and neurological diseases." (PMID 31649729, 2019).
blood cancer (7 papers, 2013 to 2025). "First, the expression levels of DNMT1, 3A and 3B and their variant types were assessed in three blood cancer model cell lines, namely KG1, HL60 and Karpas299." (PMID 25948775, 2015). "Also, expression level of DNMT1 was positively correlated with blood cancer stage." (PMID 37573395, 2023).
bacterial infection (5 papers, 2021 to 2024). "Release of the pro-inflammatory LPS upon bacterial infection of the wounds may induce the expression of Dnmt1, which in turn upregulates the expression of CD36 and downregulates the expression of SOAT1 and ABCA1, probably by a DNA-methylation-based mechanism." (PMID 37291182, 2023). "We found three genes, namely BATF, ISG15 and DNMT1, which can distinguish viral from bacterial infections in a wide range of cohorts including different pathogens, ages and populations, and with potential to become clinical biomarkers for infectious diseases in a clinical setting." (PMID 33808774, 2021). "Baradaran and his coworkers reported the induction of DNMT-1 and DNMT-2 genes following bacterial infection." (PMID 35651618, 2022).
genetic disorders (5 papers, 2017 to 2023). "Apart from KMT2A, three other CXXC-domain-containing epigenetic regulators have been linked to Mendelian diseases: KMT2B (DYS28; OMIM:617284), DNMT1 (HSN1E; OMIM:614116), and TET3 (BEFAHRS; OMIM:618798)." (PMID 35727845, 2022). "Several studies have shown that changing the DNA methylation patterns in the regulatory promoter regions of DNMT1 play an important role in the development of genetic disorders." (PMID 31754358, 2019).
metabolic disease (5 papers, 2021 to 2025). A congenital disorder (due to inherited enzyme abnormality) or acquired (due to failure of a metabolically important organ) disorder resulting from an abnormal metabolic process. "Collectively, these data suggest an effective and beneficial strategy by targeting hepatic DNMT1 for systemic improvement of metabolic disorders." (PMID 34141522, 2021). "Metabolic disorders emerge as one of the biggest public health challenges with distinctive feature of elevated free fatty acid, which can promote mitochondrial translocation of DNA methyltransferase 1 in liver, resulting in hypermethylation of NADHdehydrogenase 6 (ND6) on mitochondrial DNA." (PMID 34141522, 2021).
psychiatric diseases (5 papers, 2014 to 2024). "Finally, Dnmt1 encodes an epigenetic regulator that has been implicated in epigenetic effects of early-life stressors and in psychiatric disorders." (PMID 31031589, 2019).
neurodevelopmental disorder (4 papers, 2019 to 2025). A behavioral and cognitive disorder with onset during the developmental period that involves impaired or aberrant development of intellectual, motor, or social functions. "In this context, we extended our findings on DNMT1 dysregulation on three other neurodevelopmental disorders i.e., ASD, EPD and BPD, along with SZ in all of which, epigenetic mechanisms have been suggested to play a role." (PMID 38125006, 2023). "Herein, we describe four patients with rare neurodevelopmental disorders (SON, ZMYND11, DNMT1 and YY1-related diseases), who received a genetic assignment only in the adulthood." (PMID 35172867, 2022).
cardiac disease (3 papers, 2016 to 2023). "We now show that knockdown of DNMT1 causes significant changes in DNA methylation patterns, gene expression (including deactivation of the heart disease pathways), and function of embryonic cardiomyocytes." (PMID 34235895, 2021). "Our RNA‐Seq results also predicted deactivation of the cardiac disease pathways, which may explain the protective effects against Adriamycin‐induced pathological injury in the heart of myocardial tissue‐specific DNMT1 knockout rats." (PMID 34235895, 2021).
kidney disease (3 papers, 2019 to 2023). "To further delineate the role of DNMTi-induced ERV expression in kidney disease development, we generated mice with tubule-specific conditional inducible DNMT1 deletion, using the tubule epithelial cell-specific doxycycline-inducible (Pax8rtTA) system." (PMID 36732547, 2023). "Patients with severe kidney disease exhibited a slight increase in DNMT1 transcription, accompanied with small downregulation of MBD2." (PMID 31507612, 2019). "Hindering the progression of kidney diseases like IgAN by inhibition of DNA methylation could be an innovative therapeutic idea and at this point, DNMT1 could be a potential target." (PMID 34861820, 2021).
benign tumors (2 papers, 2012 to 2023). "Of the mucious tumors, the expression of DNMT3a, DNMT3b, and DNMT1 was not different between malignant and benign tumors." (PMID 22768205, 2012).
endocrine tumors (1 paper, 2016). "We found that DNMT1 enzymatic activity was significantly increased in the endocrine tumor tissues from MEN1 patients and Men1 KO mice as compared to normal endocrine tissues from unaffected individuals and Men1 WT control mice." (PMID 26871472, 2016). "Based on this, we examined the expression of DNMT1 in endocrine tumor tissues from MEN1 patients and Men1 KO mice." (PMID 26871472, 2016). "DNMT1 mRNA expression was significantly increased in the endocrine tumors from MEN1 patients and Men1 KO mice compared to normal by real-time RT-PCR." (PMID 26871472, 2016). "Xu's report showed that the protein level of DNMT1 was not regulated by menin in MEF cells, but we found the level of DNMT1 in endocrine tumors from MEN1 patients and Men1 KO mice was increased compared to normal." (PMID 26871472, 2016).
female reproductive diseases (1 paper, 2024). "In conclusion, the knockdown of DNMT1 upregulated the mRNA and protein levels of SLCO3A1, thereby promoting the proliferation of GCs to facilitate the growth and development of ovarian follicles, and these results provide new insights into investigations of female reproductive diseases." (PMID 38473715, 2024).
nervous system tumors (1 paper, 2024). "In general, DNMT1 expression in MB was higher than in corresponding normal tissue and other central nervous system tumors as determined from previous publications." (PMID 39107797, 2024).